PRRT2 (proline rich transmembrane protein 2)
Diseases named in the same sentence as PRRT2 in open-access papers (continued):
Sharing a sentence is not in itself a finding about the gene and the disease.
Dravet syndrome (3 papers, 2014 to 2023). "Besides the six patients with SCN1A variants who could all be classified as having Dravet syndrome, large phenotypic heterogeneity was noted among patients with PRRT2, KCNQ2, and SCN2A variants." (PMID 31572294, 2019). "In this study, we aim to widen the spectrum of phenotypes associated with PRRT2 mutations and investigate whether PRRT2 mutations are involved in febrile seizure-related epilepsy, including febrile seizures plus (FS+), generalized epilepsy with febrile seizures plus (GEFS+) and Dravet syndrome (DS)." (PMID 25522171, 2014). "Since developmental problems might not be evident at onset, some clinical features at onset could overlap between PRRT2‐positive SeLIE and SCN1A‐positive Dravet syndrome." (PMID 36775847, 2023).
Encephalopathy (3 papers, 2016 to 2025). Encephalopathy is a term that means brain disease, damage, or malfunction. "One girl with BFIS and bi-allelic variations of PRRT2 (paternally inherited variant c.649dupC and a de novo deletion of 16p11.2) displayed three episodes of encephalopathy after mild head trauma at 20 months, at three years, and at four years of age." (PMID 33126500, 2020). "Our results indicated that these defects may contribute to the severe encephalopathy caused by the rare homozygous or biallelic PRRT2 mutations." (PMID 27172900, 2016).
Anxiety (2 papers, 2021 to 2022). Intense feelings of nervousness, tension, or panic often arise in response to interpersonal stresses. "While it is possible that IFs will result in worry and anxiety (potentially unnecessarily depending on disease severity and penetrance) for patients and their families (see PRRT2 example in results above), it is also possible that such findings might be of great personal utility." (PMID 36414972, 2022).
cognitive disorder (2 papers, 2022 to 2023). A disease affects cognitive processes. "Although PRRT2 is known to be responsible for cognitive disorders, more studies are needed to assess the frequency of ID and psychiatric symptoms in PRRT2-associated syndromes." (PMID 35350397, 2022). "However, a small number of patients with PRRT2 variants have been reported to exhibit severe neurological deficits, such as focal seizures and epileptic spasms, severe seizures, cognitive impairment, or complex malformations." (PMID 37228410, 2023).
Epileptic spasm (2 papers, 2023 to 2025). A sudden flexion, extension, or mixed extension-flexion of predominantly proximal and truncal muscles that is usually more sustained than a myoclonic movement but not as sustained as a tonic seizure. "Atypical phenotypes were observed in 3 children with heterozygous PRRT2 variants; 1 child evolved from SeLIE to infantile epileptic spasms, another developed spike-wave activation in sleep, and 1 developed focal epilepsy in adolescence." (PMID 40401013, 2025).
febrile seizures (2 papers, 2014 to 2015). "As a new susceptibility gene of epileptic patients with febrile seizures, mutations of PRRT2 might underlie a broader range of seizure subtypes than what was previously suspected." (PMID 25522171, 2014).
focal epilepsies (2 papers, 2025). "For example, in the GluN cluster of patients with FCDII, we observed downregulation of GRIN1 and PRRT2, two genes causing monogenic forms of focal epilepsies, and upregulation of GLUL, pointing toward alterations of the glutamate signaling and neurotransmission in glutamatergic neurons." (PMID 40307383, 2025).
gastroenteritis (2 papers, 2015 to 2023). An inflammatory disorder that affects the upper and lower gastrointestinal tract. "Next, we performed a cohort study for CLCN6 in 48 BPEI patients without PRRT2 mutations and six patients who had convulsions associated with mild gastroenteritis." (PMID 25794116, 2015).
generalized epilepsy (2 papers, 2014 to 2025). Epilepsy that is characterized by generalized seizure types and may have typical interictal and/or ictal EEG findings that accompany generalized seizure types (for example generalized spike-wave). "Overall, there are few reports of adult-onset generalized epilepsy with pathogenic PRRT2 variants in the literature." (PMID 40401013, 2025).
glioblastoma (2 papers, 2019 to 2020). The most malignant astrocytic tumor (WHO grade IV). "Previous studies reported that proline-rich transmembrane protein 2 and CaMKIIδ are the targets for miR-30b-5p in glioblastoma and cardiac hypertrophy, respectively." (PMID 31768184, 2019).
infantile epileptic spasms syndrome (2 papers, 2020 to 2025). "One child with a heterozygous pathogenic PRRT2 variant evolved from SeLIE (seizure onset before 6 months) to infantile epileptic spasms syndrome (IESS) at 6–7 months of age (case 12)." (PMID 40401013, 2025).
ovarian carcinoma (2 papers, 2017 to 2025). A malignant neoplasm originating from the surface ovarian epithelium. "Whereas PRRT2 mutations were also frequent in both colorectal, endometrial and ovarian cancer cell lines DAB2IP mutations were mostly restricted to prostate and colorectal cancer samples." (PMID 27907910, 2017).
adrenal pheochromocytoma (1 paper, 2018). "To physiologically validate these findings, we examined the effect of PRRT2 on Ca2+-evoked exocytosis in rat adrenal pheochromocytoma (PC12) cells." (PMID 29346777, 2018).
arthropathy (1 paper, 2025). Any disorder of the joints. "We suggest testing patients who are negative for common disease‐causing variants in SeLFIE (SCN2A, SCN8A, KCNQ2, PRRT2) for the ANKH c.‐11C>T change, especially if there is evidence for a familial arthropathy." (PMID 40574727, 2025).
co-infection (1 paper, 2016). "The effect of PRRT2 silencing was reversible; co-infection of the neurons with Sh-resistant PRRT2 was able to achieve a virtually complete return of current amplitude and PPR to the levels of Scr-infected neurons." (PMID 27052163, 2016).
colorectal cancer (1 paper, 2017). A primary or metastatic malignant neoplasm that affects the colon or rectum. "Both normal prostate cell lines and a colorectal cancer cell line showed increased proliferation, migration and invasion when expressing the mutated form of PRRT2 (ΔPRRT2)." (PMID 27907910, 2017). "The frequency of PRRT2 mutation in patient samples is only second to the frequency of TGFβRII in colorectal cancer and the highest in endometrial cancer of all MSI genes." (PMID 27907910, 2017). "We found PRRT2 to be mutated in 15 out of 24 colorectal cancer patients and in 11 out of 24 endometrial cancer patients." (PMID 27907910, 2017). "Two normal prostate cell lines (PNT2C2 and RWPE-1) and one colorectal cancer cell line (HCT116) were used to assess the effect of PRRT2 in proliferation, apoptosis and migration." (PMID 27907910, 2017).
developmental and epileptic encephalopathy (1 paper, 2025). An epilepsy associated with developmental impairment that may be due to either the underlying etiology or the superimposed epileptic activity, or both. "Cerebral folate deficiency was demonstrated in nine patients (one with KCNH1-related developmental and epileptic encephalopathy, one with DHPR deficiency, one with Glut1 deficiency, one with a PRRT2 pathogenic variant, and five with no established etiological diagnosis)." (PMID 41300631, 2025).
endometrial cancer (1 paper, 2017). Primary or metastatic malignant neoplasm involving the endometrium (mucous membrane that lines the endometrial cavity). "Compared to other genes, PRRT2 displayed a very high mutation frequency in both colorectal and endometrial cancer and was selected for functional studies." (PMID 27907910, 2017). "PRRT2 was frequently mutated in both colorectal and endometrial cancer patients." (PMID 27907910, 2017). "We identified PRRT2 and DAB2IP to be frequently mutated in MMR deficient cell lines, colorectal and endometrial cancer patient samples." (PMID 27907910, 2017). "To further evaluate the significance of the mutation frequency of PRRT2 and DAB2IP in clinical MSI colorectal and endometrial cancer patient samples, we compared their frequency to the average mutation frequency for common MSI target genes published in databases (SelTarbase)." (PMID 27907910, 2017).
endometrial tumour (1 paper, 2024). "In contrast, of the more highly expressed genes in normal tissue, all except TMEM219 and PRRT2 had a gene dosage effect in endometrial tumour tissue (p < 0.0001)." (PMID 39495297, 2024).
genetic generalized epilepsy (1 paper, 2025). A generalized epilepsy that is understood to have a genetic etiology. "However, 1 individual with a whole-gene PRRT2 deletion and 16p11.2 microdeletion had childhood-onset medically refractory genetic generalized epilepsy (GGE) (case 11)." (PMID 40401013, 2025).
Hypsarrhythmia (1 paper, 2022). Hypsarrhythmia is abnormal interictal high amplitude waves and a background of irregular spikes. "Vitamin B6 allowed patients with ALDH7A1 and PNPO mutations to achieve seizure-free status, oxcarbazepine was effective for patients with SCN2A, ATP7A, WWOX, and PRRT2 mutations, and ACTH was partly effective for DOCK6 mutation patients with spasms and hypsarrhythmia." (PMID 35715422, 2022).
infantile-onset epilepsy (1 paper, 2022). Epilepsy starting in the first 12 months of life, including self-limiting and refractory seizures, and epilepsies with and without developmental disorders. "It has been previously thought that PRRT2-associated paroxysmal movement disorders (PRRT2-PxMD) are mostly manifested as infantile-onset epilepsy and post-adolescent movement disorders, and most of them have a good prognosis and do not affect cognitive development." (PMID 35715422, 2022).
language disorder (1 paper, 2025). A category of disorders characterized by an impairment in the development of an individual's language capabilities, which is in contrast to his/her non-verbal intellect. "Proband 7, a male with borderline intellectual functioning, language disorder, and EEG abnormalities, exhibited a duplication in the 16p11.2 chromosomal region, which encompasses 30 genes, such as PRRT2, PAGR1, and TAOK2." (PMID 41009966, 2025).
leukodystrophy (1 paper, 2018). Leukodystrophies are a group of rare, progressive, metabolic, genetic diseases that affect the brain, spinal cord and often the peripheral nerves. "In this regard, each of the young brothers in a recently described Utah leukodystrophy family harbors an allele pair associated with two incompletely penetrant conditions (PRRT2/childhood epilepsy and Slc27a6/leukodystrophy)." (PMID 29739804, 2018).
macrodactyly (1 paper, 2025). "Certainly, PRRT2 mutations alone cannot explain macrodactyly; therefore, the WES findings were deemed inconclusive." (PMID 40126231, 2025).
microcephaly (1 paper, 2019). A congenital or acquired developmental disorder in which the circumference of the head is smaller than normal for the person's age and sex. "The proband in our study presents unusual clinical features compared with those reported for other individuals affected with PRRT2 mutations, and congenital microcephaly, severe brain involvement, and dysmorphisms have not been previously reported in patients with this mutation." (PMID 31801583, 2019).
myoclonic epilepsy (1 paper, 2021). A group of epilepsy syndromes in which myoclonic seizures are a prominent feature. "In addition, PRRT2 mutations could be responsible for early childhood myoclonic epilepsy according to a recent research." (PMID 34041212, 2021).
Phelan-McDermid syndrome (1 paper, 2022). A rare genetic neurodevelopmental disorder characterized by neonatal hypotonia, global developmental delay, normal to accelerated growth, absent to severely delayed speech, and minor dysmorphic features. "Three patients had known genetic etiologies, which included 22q13 deletion syndrome (also known as Phelan-McDermid syndrome), PRRT2 gene mutation and genetic deletion SCX + DEPDC5." (PMID 35496067, 2022).
schizophrenia (1 paper, 2020). A major psychotic disorder characterized by abnormalities in the perception or expression of reality. "The genes HGF, PRRT2, EGR1, EGR3, C11orf87, TLR3 and PLEKHH2 have been reported in either genetic analysis or gene expression analysis of schizophrenia, and were all upregulated in fibroblasts from patients in our study." (PMID 31959813, 2020).
tonic-clonic seizures (1 paper, 2024). "Moreover, in-vivo expression of pHIL in the hippocampus mitigated acute tonic-clonic seizures induced by pilocarpine and counteracted audiogenic seizures in the PRoline-Rich Transmembrane protein 2 knockout (PRRT2 KO) mouse, a model of genetic epilepsy." (PMID 38965228, 2024).
tuberous sclerosis (1 paper, 2023). Hereditary disease characterized by seizures, intellectual disability, developmental delay, and skin and ocular lesions. "Notably, the smallest panels, applied in only two individuals with suspected tuberous sclerosis (comprising 104 and 150 genes), lacked coverage for the PRRT2 gene." (PMID 38328757, 2023).
tumor (92 papers, 2015 to 2026). "In conclusion, a focused genome-wide sequencing approach, followed by subsequent expression and functional studies indicate mutated PRRT2 as a novel dominant oncogene, and wtPRRT2 as a candidate tumor suppressor gene." (PMID 27907910, 2017). "The expression level of PRRT2 is overall lower in cancer as compared to normal, which would indicate it as a potential tumour suppressor gene." (PMID 27907910, 2017). "Targeting PRRT2 is bryostatin, a powerful protein kinase C agonist that was originally developed to prevent tumor growth, but in preclinical studies has also shown promising effects as a restorative synapse drug that is currently in trials to treat Alzheimer’s disease." (PMID 37884687, 2023). "Starting from literature evidence reporting an effect of PRRT2 expression in the migration of neuronal precursors and tumor cells, we performed a wound-healing assay in NIH 3T3 fibroblasts, to gain insight into the mechanisms underlying the effect of PRRT2 on cell motility." (PMID 33056987, 2020).
cancer (45 papers, 2014 to 2025). A tumor composed of atypical neoplastic, often pleomorphic cells that invade other tissues. "Most of the NRF2 pathway-related genes showed extensively negative relationships with RNAss; for example, the expressions of FOS, JUN, MAF, MAFK, and PRRT2 in various cancers were negatively related to RNAss." (PMID 35242279, 2022). "MDA-MB-231-derived exosomes releasing miR-454 disrupted the Wnt pathway by targeting PRRT2, thereby promoting the biological properties of cancer stem cells (CSCs) in vitro and ovarian cancer cell growth in vivo." (PMID 34707990, 2021). "miR-454 disrupted the Wnt pathway by targeting PRRT2, thereby promoting the biological properties of cancer stem cells." (PMID 34707990, 2021). "Overall, PRRT2 showed a consistent decrease in expression in cancer as compared to normal in prostate, lung and gastric tissue samples." (PMID 27907910, 2017). "To investigate a possible role of PRRT2 in cancer we first documented PRRT2 expression levels by RNA sequencing in available cancer data sets." (PMID 27907910, 2017). "We identified proline-rich transmembrane protein 2 (PRRT2) and DAB2 interacting protein (DAB2IP) to be frequently mutated in all different cancer cell line types." (PMID 27907910, 2017). "The wild-type PRRT2 (PRRT2wt) had an inhibitory effect in proliferation, consistent with the low expression level of PRRT2 in cancer versus normal prostate samples." (PMID 27907910, 2017). "Also here we identified CNOT1, DAB2IP and PRRT2 as novel MSI target genes, in the MMR-deficient cancer cell lines, although with varying frequency." (PMID 27907910, 2017). "Next, we checked whether the mutation frequencies of PRRT2 and DAB2IP observed in the cancer cell line panels could be confirmed in primary cancer samples." (PMID 27907910, 2017). "However mutations in this gene only affect one of the copies in almost all affected cancers, leaving a wild type PRRT2 copy intact." (PMID 27907910, 2017). "Further characterization of PRRT2 revealed an important role of this gene in cancer biology." (PMID 27907910, 2017).